IL18 (interleukin 18)
Diseases named in the same sentence as IL18 in open-access papers (continued):
Sharing a sentence is not in itself a finding about the gene and the disease.
tumor (continued). "Therefore, IL-18 and IP-10/CXCL10 in NPC may play dual roles in the recruitment and suppression of CXCR3+ tumor infiltrating NK cells and T cells." (PMID 33718235, 2021). "In our study, the expression pattern of pro-IL-18 expression by tumor cells did not significantly influence overall survival in univariate or multivariate analyses (not shown), a finding consistent with a previous study performed in silico using cancer gene expression databases." (PMID 33430344, 2021). "The secretion of IL-12 or IL-18 by CAR T cells may be able to raise local concentrations of these cytokines within the TME, potentially enhancing CAR T cell function itself, as well as creating a more favourable immune landscape within the tumour." (PMID 34885108, 2021). "Finally, and unexpectedly, we identified a “paradoxical” subgroup of CRC (n = 33/96 (34%)) that did not display any IFNγ response although they produced mature IL-18 and featured aCasp1+ tumor cells in 50% of cases." (PMID 33430344, 2021). "Studies have suggested the role of IL-18 in the polarization of T cells toward Th1 or Th2 cells by inducing IL-17 expression in Th17 cells in certain types of cancer, while the role of IL-18 in tumor progression has not been fully elucidated yet." (PMID 34684819, 2021). "Accordingly, monocytes cultured with NK cells and K562 cells (or RCC cell lines, not shown) produced similar amounts of IL-18 than PBMC cultured with tumor cells, and separation of monocytes from NK cells and tumor cells by transwells abrogated IL-18 secretion (not shown)." (PMID 34616407, 2021). "Interestingly, at the low E:T ratio of 0.5:1, only IL-2/IL-12/IL-18-pretreated γδ T cells exhibited a sustained anti-tumor effect, in fact irrespective of a simultaneous TCR stimulus." (PMID 31947966, 2020). "Interestingly, IL-18 not only augments both NK and iNKT cell activity via IFN-γ production, but it also acts synergistically with IL-12 to enhance the cytotoxicity of these cells against tumor targets." (PMID 32708464, 2020). "In addition, in patients with higher NLR, the cytokines released by neutrophils, including interleukin-18 (IL-18), vascular endothelial growth factor (VEGF), together with matrix metalloproteinases (MMP), may contribute to tumor growth." (PMID 33392090, 2020). "Additionally, IL-18 also induces the expression of CD80, CD86, HLA-DR and HLA-DQ on NK cells derived from cancer patients, suggesting that IL-18 conferred NK cells on an APC-like phenotype, which indicates increased recognition and responsiveness to tumour antigens." (PMID 32168834, 2020). "Our results suggest that pMSCs might enhance the anti-tumor activities of NK cells through IL1ra or via other mediators including IL12, IL-18, and IFNγ receptors and their corresponding cytokines (IL-18, IL-12, and IFNγ), which are known to be involved in the anti-tumor activity of NK cells." (PMID 30728068, 2019). "Additionally, there was also a negative correlation with tumor purity and the infiltration of most immune cells increased along with IL18 expression in SARC and BRCA." (PMID 31731729, 2019). "Considering that also tumor cells may represent a source of MMPs, TGF-β1, and IL-18, the combined effect of TGF-β1 and IL-18, supported by the proteases intervention, might play a pivotal role during M2 polarized immune responses occurring in the tumor microenvironment." (PMID 30641867, 2019). "IL-18 in combination with IL-12 can activate cytotoxic T cells (CTLs), as well as natural killer (NK) cells, to produce IFN-γ and, therefore, may contribute to tumor immunity." (PMID 31554361, 2019). "However, IL18 expression did not have any correlation with tumor purity or immune infiltration in COAD which was used as a negative control." (PMID 31731729, 2019). "Therefore, it is probable that decreased expression of IL-18 in the current study may have abrogated the expression of VCAM-1, which possibly contributed to the reduction of tumor incidence." (PMID 30401976, 2018).
tumor (continued). "Although mechanisms responsible for IL-18 membrane retention and release have to be clarified, this cytokine shows many predictable cleavage sites for extracellular proteases such as Matrix metallopeptidase (MMP) −2 and −9, which characterize the secretory profile of parenchymal tumor cells and TAM." (PMID 30364222, 2018). "In multiple tumor models, IL-18 upregulated PD-1 expression on mature natural killer cells only in lymphoid organs but not in tumors; anti-PD-1 therapy in vivo abrogated IL-18-mediated metastases." (PMID 29255458, 2017). "In addition, our western blot results showed that NLRP3, Caspase-1, IL-18 and IL-1β were highly expressed in the Tgfbr1/Pten 2cKO mice SCCHN tumor lysates compared with control wild type tongues, and the expression of BMI1, ALDH1 and CD44 were consistent with NLRP3 inflammasome." (PMID 28865486, 2017). "Although simultaneous VP3, interleukin-24, interleukin-18, upregulations and survivin downregulation seemed to show greater anti-tumor activity than VP3 alone, the combined effect of VP3 and shRNA on CD147 affecting tumor growth and progression is yet to be investigated." (PMID 27411985, 2016). "Thus, our data suggest that IL-15 and IL-18 cytokines could be utilized in combination with BRAF/MEK inhibitors to sustain and/or activate NK cell anti-tumor potential in vivo." (PMID 27563819, 2016). "Our preliminary data show that tumor growth was not reduced in IL-18 KO mice, indicating that IL-1β and IL-18 may have different or even opposite roles in tumor development (Guo, unpublished results)." (PMID 27786298, 2016). "Importantly, PD0325901 did not affect the anti-tumor activity of NK cells that had been exposed to a combination of IL-15 and IL-18." (PMID 27563819, 2016). "Conversely, the tumor-promotional neutrophils recovered the expression of Rab27a and Trail, resumed the activation levels of PI3K and p38 MAPK pathways in response to stimuli, and expressed higher levels of IL-18 and NK-activating ligands such as RAE-1, MULT-1, and H60." (PMID 25587026, 2014). "However, systemic administration of recombinant human IL-18 into cancer patients, as reported in three clinical trials, did not lead to overt anti-tumor efficacy." (PMID 21935389, 2011). "In order to discard that the increase in plasma IL-18 might reflect a decreased hepatic metabolism of this cytokine subsequent to the metastasis process, we next determined the effect of RVL on IL-18 secretion from tumor-activated hepatic sinusoidal cells." (PMID 21569399, 2011). "NK cells may play a role as depletion of this cell type appeared to inhibit the anti-tumor effect of IL-18, although the difference was not statistically significant in these studies." (PMID 21935389, 2011). "Based on our work, we speculate that this route of administration of IL-18 does not deliver therapeutic doses of the cytokine to the tumor to induce anti-tumor responses." (PMID 21935389, 2011). "Interestingly, in our studies with tumor-bearing mice, intratumoral injection with an IL-18 plasmid did not prevent CT26 tumor development, although augmentation of T cells and maintenance of the IFN-γ level during 2 weeks appeared to reject tumors." (PMID 17519043, 2007). "Our results suggest that direct plasmid DNA transfer of IL-18 with no accompanying reagents to augment transfection efficiency may be useful in tumor immunotherapy." (PMID 17519043, 2007). "Importantly, IL-18 is necessary to activate NF-κB and boost the antitumor activity associated with HIF-1α; in its absence, NK cells lacking HIF-1α cannot effectively control tumor progression." (PMID 40297580, 2025). "IL-18 may accelerate tumor growth, especially in the absence of Th1-like cytokines." (PMID 41179937, 2025). "However, as they rely on endogenous IL-18, they may also have lower efficacy and may not be effective for all tumor types or anatomic sites of disease, depending on patterns of IL-18 expression." (PMID 39561007, 2024).
tumor (continued). "IL-1β, as opposed to IL-18, may play a dominant role in mediating anti-tumor immunity." (PMID 38391959, 2024). "However, high IL‐18 levels suggest severe immunosuppressive conditions in the tumor milieu that could not be sufficiently improved by Ld treatment." (PMID 39031503, 2024). "Additionally, IL-18 promotes the differentiation of T cells towards a Th1 phenotype; Th1 cells produce IFN-γ and activate macrophages and other immune cells that contribute to anti-tumor immunity, making this shift towards a Th1-dominated response crucial for effective anti-tumor activity." (PMID 38957317, 2024). "We hypothesized that addition of IL-18, which can induce the proliferation of several immune effector cells through inducing IFNγ, major histocompatibility complex (MHC) class I expression, and also by inhibiting angiogenesis, could synergize with IL-27 to enhance tumor growth control." (PMID 34209203, 2021). "However, unlike normal colonic epithelial cells they derive from, a variable proportion of tumor cells per tumor exhibits an aberrantly activated inflammasome (expression of active caspase-1 and release of mature IL-18), irrespective of the microsatellite status." (PMID 33430344, 2021). "In addition to IL-12 and IL-18, CAR T cells engineered to secrete IL-7, IL-15, and IL-21 (covered in more detail in the next section), although primarily intended to enhance the persistence and activity of the CAR T cells themselves, will also stimulate anti-tumour responses in bystander cells." (PMID 34885108, 2021). "In regards to the ex vivo expansion setting, we could not distinguish any superiority in terms of anti-tumor activity in vivo among IL-7, IL-15, IL-18, IL-21 and no cytokine (NC) conditions, perhaps due to CART cell number being sufficient to eliminate tumor in all the groups." (PMID 27409425, 2016). "Additionally, mice immunized with E7 DNA vaccine combined with individual adjuvants in the presence of isotype control mice did not reveal further protection against tumor over E7 DNA vaccine combined with individual adjuvants in the presence of anti-IL-18 mAbs." (PMID 26811064, 2016). "A similar 5 day-RVL pretreatment schedule as above also completely abrogated the augmentation of IL-18 concentration in the hepatic blood obtained 18 hours after B16M cell injection into treated mice, without affecting the physiological levels of this cytokine in mice not injected with tumor cells." (PMID 21569399, 2011). "In tumors, IL-18/IL-12-stimulated γδ T cells directly kill cancer cells and induce senescence in the absence of TCR signaling, exerting potent anti-tumor activity." (PMID 41522514, 2026). "Finally, the development of CAR-T cells engineered to secrete proinflammatory cytokines (such as IL-12, IL-15 and IL-18), to produce molecules engaging tumor cells by not engineered T cells, as well as the development of strategies to overcome cell exhaustion could also be required." (PMID 40092980, 2025). "Meanwhile, the mRNA and protein expression levels of NLRP3, caspase 1, GSDMD, IL-1β and IL-18 in H(FMT) group were higher than that in T(FMT) group, while there were no noticeable difference between T(FMT) group and tumor model group." (PMID 40046008, 2024). "CART significantly impaired but did not abrogate anti-tumor response in mice receiving combination treatment, supporting that IMSA101 enhances CART response through IL18-mediated as well as independent mechanisms." (PMID 38730243, 2024). "IL-18 and GSDMD, both constituents of the canonical pathway of pyroptosis, were also upregulated in the tumor samples that were assessed, further proving the activation stage of pyroptosis in BC." (PMID 37511974, 2023). "In this report, there was a significant negative correlation between IL-18, MCP-1, and glutathione, implicating direct anti-tumor immunity of Interferon-γ (IFN-γ) producing T helper type 1 (Th1) cells." (PMID 36503580, 2022).
tumor (continued). "CXCR3+ T cells and NK cells recruited to the TME by IL-18 and IP-10/CXCL10 are unlikely to possess anti-tumor function, although they are active in IFNγ production." (PMID 33718235, 2021). "Based on this mechanism, it is believed that IL-18 and IP-10/CXCL10 do not exert tumor-suppressive effects, but rather, promote IFN-γ secretion and chemoattraction of CXCR3+ cells into the NPC TME." (PMID 33718235, 2021). "Our results indicated that cleaved IL-1β and IL-18 were extremely low, regardless of the expression level of AIM2 in tumor cells." (PMID 33391539, 2021). "Plasma levels of the NK cell-activating cytokines IL-2, IL-15, IL-18, and IL-21 increased substantially within the first 2 days after CY+TBI compared to their plasma levels in 4T1 tumor-bearing mice not subjected to chemo-irradiation." (PMID 27915436, 2017). "Tumors in mice receiving IL-7, IL-15, IL-18, IL-21, and NC exposed CART cells regressed or even disappeared, without any statistical difference in tumor size at the end point." (PMID 27409425, 2016). "Levels of proinflammatory cytokines IL-1β, IL-18, Tumor Necrosis Factor (TNF)-α and Interferon (IFN)-γ were decreased in the tumor microenvironment in the absence of inflammasome proteins." (PMID 25268644, 2014). "Although most of these chronic models did not evaluate potential alterations in anti-tumor adaptive immunity, one study showed that in the absence of NLRP3 and caspase-1, reduced IL-18 in a colorectal tumor model led to diminished IFN-γ levels in the colon." (PMID 24409181, 2013). "Notably, cerebrospinal fluid and peripheral blood monocytes are major sources of IL-6, IL-18 (a chemokine subclass), and TNF-α (which selectively targets tumor cells without significant toxicity to normal cells)." (PMID 41458177, 2025). "In agreement with the upregulation of MHC, we also observed a strong enrichment in interferon signaling for effective tumor-suppressing treatments, particularly for NT GSDMD + IL-12, as well as for ineffective NT GSDMD + IL-1β + IL-18 treatment, although not necessarily with the same genes." (PMID 39737979, 2024). "They verified in vitro that deficiency of IL-18 could suppress the cytotoxicity of NK cells and CD8+ T cells, indicating that the absence of IL-18 is likely to mediate the IFN-γ pathway during tumorigenesis in ESCC and lead to AR in anti-tumor immunity." (PMID 36119033, 2022). "Interestingly, our results revealed that priming of tumor cells with LPS increased the release of IL1-β and IL-18 without the requirement for the second stimulus (Nigericin)." (PMID 33613529, 2020). "A possible explanation for the lack of increased NLRP3 expression, despite elevated caspase-1, IL1β and IL18, is that only specific locations have cells with activated NLRP3 (i.e., a cluster of invading immune cells at the tumor/tissue interface) and tissue was from regions without altered NLRP3." (PMID 31923221, 2020). "NK cells are large granular lymphocytes that express neither α/β or γ/δ TCR nor CD3 on their surface, can lyse a number of different tumour cells and may be stimulated by IFN-γ, IL2, IL12 and IL18." (PMID 20500874, 2010). "Interestingly when looking into mouse IL-18 production either in tumour-free or in tumour-bearing (not shown) NSG mice, we found that haematopoietic CD45+ and non-haematopoietic CD45− cells could produce IL-18, suggesting that BM cells constitute a reservoir of IL-18." (PMID 24778454, 2014).
infection (883 papers, 2006 to 2026). The state of being infected such as from the introduction of a foreign agent such as serum, vaccine, antigenic substance or organism. "Research has confirmed that the variation in the IL-18 rs1946518 genotype is significantly associated with an increased infection risk." (PMID 41376789, 2025). "Danger signal-induced inflammasome activation drives caspase-1-mediated cytokine secretion (e.g., IL-1β/IL-18) and lytic cell death (pyroptosis), which are critical for host defense against pathogenic infections or tissue damage." (PMID 41208996, 2025). "In contrast, IL-18 has been shown to promote a Th2 response and host susceptibility in experimental infections with L. (L.)mexicana and L. (L.)amazonensis." (PMID 40431153, 2025). "The functional variant rs2043055, which is located in an enhancer region of IL18 expression, was associated with infection in two Colombian cohorts and with CCC severity in a Brazilian cohort with 1051 patients." (PMID 40297326, 2025). "Early-gestation infection was associated with increased levels of eight inflammatory biomarker, including TNSF14, TGF-α, EN-RAGE, and decreased IL-18 levels, while late-gestation infection was linked to elevations in 12 biomarkers, including CD5, CD6, PD-L1." (PMID 41510260, 2025). "Our data showed that Il18−/− mice were more susceptible to infection, which was mediated by the decrease in IFN-γ production." (PMID 40315193, 2025). "Supplementation of IL-18 into IL-22 deficient mice restored mucin secretion, indicating that IL-22 acted upstream of IL-18 secretion during infection." (PMID 39428744, 2024). "Despite its discovery in 1995, IL‐18 has been acknowledged as a multifunctional cytokine inducing diverse biological effects associated with infection, inflammation, and autoimmune processes." (PMID 39188114, 2024). "In contrast, IL-18 and IL-22 independent signaling through Nlrp6 underlies only a modest, infection-induced increase in mucin secretion from goblet cells in the distal colon." (PMID 39428744, 2024). "Trophoblasts produce cytokines constitutively and in response to infection, including those associated with the inflammasome, such as IL-1β and IL-18, which control L. monocytogenes infection." (PMID 38771057, 2024). "In DevF2 follicles, there was a higher transcript level of the IL18 gene, which codifies a pro-inflammatory cytokine with a pivotal role in host defense by regulating genes associated with inflammation, infection, and malignancy." (PMID 39468655, 2024). "The cytokines that are crucial for protective responses against infection are linked to Th-1 cells, such as IL-12, IL-18, and IFN-γ." (PMID 38667922, 2024). "While CDT contributes to increased weight loss and cecal edema at 2 days post infection, the relative levels of inflammasome-associated cytokines, IL-1β and IL-18, in the cecum and distal colon are unchanged." (PMID 39298531, 2024). "The significance of IL-18 in establishing NK cell activity is evident in IL-18 deficient mice, where susceptibility to infection increases due to impaired NK cell function." (PMID 39554494, 2024). "The functional role of IL-18 in disease progression was examined using a subcutaneous infection model and IL-18-deficient mice." (PMID 37910490, 2023). "Mice are frequently used to model infection, but only a few instances have il18-/- mice are susceptible to infection." (PMID 37068092, 2023). "Conversely, expression of the pro-inflammatory IL18 in the jejunum was significantly decreased by infection (fold change − 1.2), and so were type-2 associated gene CCL22 (fold change − 2.1) and adipocyte regulator PPARG (fold change − 1.3)." (PMID 38081984, 2023). "Δ6 Yptb infection of two independent clones of CASP1−/− Caco-2 cells resulted in a partial loss of IL-18 release compared to WT Caco-2 cells." (PMID 37615436, 2023). "We also examined the functional roles of IL-18 in disease progression using an IL-18-deficient mouse model with subcutaneous infection." (PMID 37910490, 2023).